KCNS1 (potassium voltage-gated channel modifier subfamily S member 1)
Description:
Each regulatory subunit has unique regulatory properties that can lead to extensive inhibition, significant changes in kinetics, and/or substantial shifts in the voltage dependencies of the inactivation process (By similarity).
Synonyms: hKv9.1; Kv9.1
Tractability: Small molecule: an approved drug acts on it; it belongs to a druggable protein family. Antibody: UniProt places it where antibodies can reach, with high confidence; its Gene Ontology location is reachable by antibodies, with high confidence; UniProt predicts a signal peptide or a membrane-spanning region.
Gene: Protein-coding gene on chromosome 20 (45,091,214 to 45,101,127, reverse strand). Ensembl gene ENSG00000124134.
Subcellular location: Cell membrane
Subcellular location (Human Protein Atlas): Plasma membrane; Vesicles; Nucleoplasm
Pathways (Reactome):
Neuronal System: Voltage gated Potassium channels
Gene Ontology:
Molecular function: potassium channel regulator activity; protein binding; monoatomic ion channel activity; voltage-gated potassium channel activity
Biological process: regulation of potassium ion transmembrane transport; action potential; potassium ion transmembrane transport; potassium ion transport; monoatomic ion transport; protein homooligomerization; transmembrane transport
Cellular component: plasma membrane; voltage-gated potassium channel complex; membrane; perinuclear region of cytoplasm
Genetic constraint (gnomAD): Loss-of-function variants: 28 observed, 29.24 expected, observed/expected ratio (o/e) 0.96, 90% interval 0.71 to 1.31. The upper end of that interval is the gene's LOEUF score, 1.31, which puts it in group 5 of 6, group 1 being the genes least tolerant of losing a copy. Missense variants: 673 observed, 643.15 expected, observed/expected ratio (o/e) 1.05, 90% interval 0.98 to 1.12. Synonymous variants: 292 observed, 282.76 expected, observed/expected ratio (o/e) 1.03, 90% interval 0.94 to 1.14.
Homologues: Orthologues: chimpanzee KCNS1 (99% identical), macaque KCNS1 (97% identical), dog KCNS1 (87% identical), pig KCNS1 (87% identical), rat Kcns1 (85% identical), mouse Kcns1 (85% identical), guinea pig KCNS1 (84% identical), tropical clawed frog kcns1 (56% identical), rabbit KCNS1 (54% identical), zebrafish si:dkey-43k4.5 (53% identical). Paralogues in human: KCNS2 (45% identical), KCNS3 (42% identical), KCNB2 (34% identical), KCNV1 (33% identical), KCNV2 (32% identical), KCNG1 (30% identical), KCNG2 (29% identical), KCNG4 (29% identical), KCNF1 (28% identical), KCND1 (27% identical), KCNA7 (26% identical), and 19 more.
Diseases named in the same sentence as KCNS1 in open-access papers:
KCNS1 is named in the same sentence as 14 diseases in open-access papers, as found by Europe PMC text mining. Sharing a sentence is not in itself a finding about the gene and the disease. The quoted sentences say what the papers report.
epilepsy (3 papers, 2013 to 2023). A brain disorder characterized by episodes of abnormally increased neuronal discharge resulting in transient episodes of sensory or motor neurological dysfunction, or psychic dysfunction. "We identified four key potassium channel genes, KCNA1, KCNA2, KCNJ11, and KCNS1, that are associated with the pathogenesis of epilepsy." (PMID 37483435, 2023). "Previous research has shown that three of the four key potassium channel genes (KCNA1, KCNA2, KCNJ11, and KCNS1) play vital roles in seizures and epilepsy." (PMID 37483435, 2023). "In particular Kv8.2 (KCNV2) with epilepsy and Kv9.1 (KCNS1) with chronic pain." (PMID 24062639, 2013). "However, the involvement of KCNJ11 and KCNS1 in epilepsy has not been reported thus far, and it was first found that the mRNA and protein levels of these two genes were downregulated in TLE samples compared to normal controls, which remains to be confirmed by further studies." (PMID 37483435, 2023).
breast carcinoma (2 papers, 2022 to 2024). "For instance, KCNS1 and LBX1 are implicated in the metastasis of breast cancer." (PMID 38544827, 2024).
COVID-19 (1 paper, 2021). A disease caused by infection with severe acute respiratory syndrome coronavirus 2. "The proximity score of promethazine was significantly low partly by targeting genes including CALM1, KCNS1, LPAR4, LPAR6, P2RY12, P2PY8, and P2RX5, which were DEGs between T cell subsets of COVID-19 samples and healthy controls." (PMID 33919660, 2021).
diabetic neuropathy (1 paper, 2022). A chronic, pathological complication associated with diabetes mellitus, where nerve damages are incurred due to diabetic microvascular injury involving small blood vessels that supply these nerves, resulting in peripheral and/or autonomic nerve dysfunction. "Five of them, KCNA2, KCNA4, KCNQ5, KCNN1 and KCNS1, were also negative for screening in a diabetic neuropathy population." (PMID 36430572, 2022).
endometrial carcinoma (1 paper, 2022). A malignant tumor arising from the epithelium that lines the cavity of the uterine body. "Bioinformatics analysis inferred that a low rate of miR-670/KCNS1 ratio in patients with endometrial carcinoma had significantly poorer survival." (PMID 35882857, 2022).
lung adenocarcinoma (1 paper, 2023). A carcinoma that arises from the lung and is characterized by the presence of malignant glandular epithelial cells. "Expression of KCNF1 and KCNV2 was significantly increased, while expression of KCNS1 was decreased in lung adenocarcinoma." (PMID 36385523, 2023).
lung carcinoma (1 paper, 2023). "To determine the role of KvS subfamilies in NSCLC, we explored the lung cancer datasets from The Cancer Genome Atlas (TCGA) to inquire expression levels of KCNF1 (Kv5.1), KCNG4 (Kv6.4), KCNV2 (Kv8.2), and KCNS1 (Kv9.1)." (PMID 36385523, 2023).
cancer (2 papers, 2019 to 2025). A tumor composed of atypical neoplastic, often pleomorphic cells that invade other tissues. "Besides the downregulated expression level of KCNS1 in metastatic breast carcinoma, little research has been carried out on the relationship between KCNS1 and cancer." (PMID 31481972, 2019).
KCNS1 also shares sentences with these, for which no sentence is quoted: injury (2 papers); depression (1); hepatocellular carcinoma (1); neuropathic pain (1); Pain (1); peripheral nerve injury (1).